INS (insulin)
Diseases named in the same sentence as INS in open-access papers (continued):
Sharing a sentence is not in itself a finding about the gene and the disease.
type 2 diabetes (continued). "Insulin degludec is a once-daily basal insulin with an ultra-long duration of action, approved for use in adults, adolescents and children with either type 1 or type 2 diabetes." (PMID 28913543, 2018). "Clinical studies involving diabetes type 2, congestive heart failure, and obesity had correlated echocardiographic findings with insulin and lipid profile." (PMID 30400581, 2018). "These brief questionnaires complement measures of treatment efficacy and provide a more thorough picture of patients’ experiences with non-insulin injectable treatments for type 2 diabetes." (PMID 30294714, 2018). "The mechanism of exercise effect on GDM was similar to type II diabetes and stated that exercise probably increased sensitivity to insulin." (PMID 30788294, 2018). "Because IGFBP1 expression is strongly regulated by insulin, it serves as an excellent marker of IR in type 2 diabetes patients." (PMID 29777116, 2018). "HOMA-β, a measure of insulin secretion, has also been found to initially parallel rising TG levels in newly diagnosed type 2 diabetics only to decrease as TG levels continued to rise higher." (PMID 30473679, 2018). "We then assessed the relationship between rCP and questionnaire-based measures of hypoglycaemia in 256 patients with insulin-treated type 2 diabetes and a comparison group of 209 individuals with type 1 diabetes." (PMID 28983693, 2018). "In previous investigations of healthy individuals and in patients with type 2 diabetes, addition of guar gum to a standard oral glucose load or test meal dampened post-prandial rise in plasma insulin and gastric inhibitory polypeptide." (PMID 30170579, 2018). "In the current study, instead of recapitulating the hyperinsulinemia typically seen in type 2 diabetes, DIO-STZ mice instead develop hypoinsulinemia, which is attributed to STZ-induced loss of insulin-producing β-cells." (PMID 30446513, 2018). "Sheu WH, Ji L, Lee WJ, Jabbar A, Han JH, Lew T. Efficacy and safety of premixed insulin analogs in Asian patients with type 2 diabetes: a systematic review." (PMID 29527102, 2018). "The disruption of Akt1 in mice causes no significant perturbations in metabolism, whereas mice knocked-out for Akt2 show insulin resistance, with a phenotype closely resembling type 2 diabetes of humans." (PMID 30170598, 2018). "In insulin-treated type 2 diabetes, in one observational study, the prevalence of IAH was reported to be ~10%, although confirmatory data are lacking." (PMID 28660491, 2018). "Impaired glucose-stimulated insulin secretion (GSIS) by pancreatic beta cells (β-cells) contributes to the hyperglycemic state that characterizes type 2 diabetes." (PMID 29953508, 2018). "Decreased muscle GU, increased endogenic hepatic glucose production (EGP) and impaired insulin secretion contribute to hyperglycemia and type 2 diabetes." (PMID 29535167, 2018). "In DEVOTE, patients with type 2 diabetes were randomised to receive either insulin degludec or insulin glargine U100 (100 units/ml) once daily (between dinner and bedtime) in an event-driven, double-blind, treat-to-target cardiovascular outcomes trial." (PMID 28913543, 2018). "Type 1 diabetes occurs due to the inability of the pancreas to produce insulin, whereas type 2 diabetes occurs due to cells developing a resistance to insulin." (PMID 29439941, 2018). "The Janus face role of fatty acids (FAs) in relation to insulin secretion and the development of pre-diabetic and diabetic states of type 2 diabetes are discussed in this review." (PMID 29921789, 2018). "Type 2 diabetes is typically characterized by a decrease in the efficacy of insulin in the body; i.e., reduced insulin sensitivity." (PMID 29971046, 2018). "Blood glucose levels are elevated in type 2 diabetes (T2DM) due to impaired insulin secretion resulting from declining β-cell function; decreased glucose uptake by tissues such as muscle, liver, and fat; and increased hepatic glucose production (HGP)." (PMID 29556139, 2018).
type 2 diabetes (continued). "AGM improved glucose metabolism and lipid profiles in insulin insufficient type 2 diabetic rats, with Asian type 2 diabetes." (PMID 30041479, 2018). "β cell dysfunction-mediated imbalance of insulin sensitivity, followed by the development of insulin resistance, triggers pathogenesis of type 2 diabetes." (PMID 30044774, 2018). "Although ketosis diets lowered basal blood glucose and insulin levels in normal mice and murine models of type 2 diabetes, these diets also produced glucose intolerance, as well as hepatic and whole body insulin resistance." (PMID 31061673, 2018). "High-intensity interval training robustly enhances skeletal muscle oxidative capacity and insulin sensitivity in adults with Type-2 diabetes." (PMID 30093853, 2018). "This intervention with a Paleolithic diet in overweight individuals with type 2 diabetes showed decreased ectopic lipid accumulation in liver and soleus muscle, as well as improved peripheral insulin sensitivity." (PMID 29696296, 2018). "It will be relevant to study the fixed ratio of glucagon and insulin in a type 2 diabetic animal model where a higher insulin dose is needed because of more insulin resistance." (PMID 29595915, 2018). "For example, DNA methylation near known type 2 diabetes loci (for example, KLF14, ZNF518B, INS) is associated with measures of glucose homeostasis (HbA1c, 2 h insulin) in healthy individuals." (PMID 29159468, 2018). "The steady state plasma insulin during hyperinsulinemic euglycemic clamp in healthy subjects is lower than that in type 2 diabetes patients in the present study." (PMID 29791512, 2018). "Aronia and its anthocyanins have anti-inflammatory and antioxidant properties that improve insulin sensitivity and prevent type 2 diabetes." (PMID 30041479, 2018). "The limited supply of islet donors and the need for chronic treatment of recipients with immunosuppressors restrict the applicability and long-term efficacy of islet transplantation in patients with type 1 diabetes or type 2 diabetes who require insulin." (PMID 30150605, 2018). "Mohan V, Kalra S, Kesavadev J, Singh AK, Kumar A, Unnikrishnan AG, Chawla R, Mukherjee JJ, Sahay RK, Kumar10 JS, Bhoraskar11 A. Consensus on initiation and intensification of premix insulin in type 2 diabetes management." (PMID 29527102, 2018). "Mir-103 and mir-107 were noted to be upregulated in obese mice and were subsequently found to have a key role in insulin sensitivity making them potential targets for the treatment of type-2 diabetes." (PMID 29995913, 2018). "Type 2 diabetes mellitus (T2DM) is characterized by abnormally elevated levels of blood glucose due to impaired insulin secretion, glucose intolerance, and hyperglycemia." (PMID 30533447, 2018). "To identify the hub genes and determine how well node2vec captures the relatedness between these hubs, we constructed an extended type 2 diabetes pathway network using other 2 pathways: insulin signaling pathway and adipocytokine signaling pathway." (PMID 29897325, 2018). "It has been well established that individuals with type 2 diabetes can benefit from exercise-induced improvements in glycaemia control and insulin sensitivity." (PMID 30199540, 2018). "Type 2 Diabetes Mellitus (T2DM) is characterized by improper insulin signalling and attenuated glucose uptake into cells." (PMID 30276216, 2018). "Hallmarks of type 2 diabetes include chronically elevated blood glucose levels due to decreased insulin secretion from pancreatic beta cells and insulin resistance in different tissues." (PMID 29164275, 2018). "Haak T, Hanaire H, Ajjan R, Hermanns N, Riveline JP, Rayman G. Flash glucose-sensing technology as a replacement for blood glucose monitoring for the management of insulin-treated type 2 diabetes: a multicenter, open-label randomized controlled trial." (PMID 29527102, 2018).
type 2 diabetes (continued). "Targeting peroxisome proliferator-activated receptor γ (PPARγ) by synthetic compounds has been shown to elicit insulin sensitising properties in type 2 diabetics." (PMID 30906767, 2018). "This study evaluated the implementation of a mobile intervention to titrate basal insulin for uncontrolled type 2 diabetes patients (“MITI”), as it became usual care at 2 ambulatory clinics in NYC." (PMID 29555621, 2018). "In 2010, a high molecular weight leaves extract (1 g/day for 60 days) was found to significantly increase the circulating insulin and C-peptide levels and reduced fasting and post-prandial blood glucose in a small cohort of patients with type 2 diabetes." (PMID 29300317, 2018). "Pioglitazone (PGZ) is a PPAR-γ activator that increases tissue sensitivity to insulin and is widely used to treat type 2 diabetes mellitus (T2DM)." (PMID 30966351, 2018). "With incretin-based therapies such as DPPIVi becoming increasingly popular in the treatment of type 2 diabetes, it is of clinical importance to assess the efficacy and safety of the combination of DPPIVi therapy with basal insulin." (PMID 29370218, 2018). "GLP-1R activation stimulates β-cell proliferation in the pancreas by recruiting stem cell, increases glucose-dependent insulin secretion, and lowers blood glucose in patients with T2D (type 2 diabetes)." (PMID 30518432, 2018). "Since SIRT1, participates in regulation of glucose homeostasis through regulating hepatic glucose production, lipid metabolism and insulin production, and sensitivity, indicates its potential role to control hyperglycemia in type 2 diabetes." (PMID 30072892, 2018). "A cross-sectional study was conducted among 400 insulin users with Type 1 or Type 2 diabetes treated in outpatient endocrinology units of four large tertiary care hospitals in Nanjing, Chongqing, Beijing and Zhengzhou." (PMID 29699587, 2018). "If women with type 2 diabetes fail to respond to these glucose-lowering drugs over time, insulin (analogue) treatment is required." (PMID 29486734, 2018). "The primary objective of the study was to compare the PD properties of two different doses of the basal insulin analogs detemir and glargine in patients with type 2 diabetes and a BMI > 35 kg/m2." (PMID 30114246, 2018). "In parallel, previous studies reported that the combination of Cr and biotin is more efficient in modulating insulin, glucose and lipid metabolism in type 2 diabetes patients." (PMID 30219082, 2018). "In contrast, insulin sensitivity was lower in patients with type 2 diabetes than in patients with type 1 diabetes or healthy individuals." (PMID 30159333, 2018). "In the US and Europe, saxagliptin has been approved for use in patients with type 2 diabetes, both as monotherapy and in combination with metformin, a sulfonylurea, thiazolidinedione, or insulin, and also in combination with metformin plus insulin." (PMID 29787616, 2018). "Insulin monotherapy compared with the addition of oral glucose‐lowering agents to insulin for people with type 2 diabetes already on insulin therapy and inadequate glycaemic control." (PMID 29527102, 2018). "Logistic regression models were used to determine the associations of the glycaemic markers, fasting insulin and HOMA-IR with incident type 2 diabetes." (PMID 29018885, 2018). "Type 2 diabetes (T2D) is a chronic metabolic disorder resulting from defects in insulin secretion, insulin action or both, leading to hyperglycemia." (PMID 30587761, 2018). "This was the first randomised, controlled trial on the effects of a long term IHI on FBG, insulin sensitivity and the targeted regulatory factors involved in skeletal muscle glucose uptake and insulin signalling pathway in mice with type 2 diabetes." (PMID 30199540, 2018). "The sRAGE levels were raised in type 2 diabetic patients who were treated with a combination of antidiabetic medications such as gliclazide (sulfonylurea), metformin and insulin." (PMID 29610703, 2018).
type 2 diabetes (continued). "High levels of blood glucose are typically accompanied by increased production of free radicals, independently from insulin availability in patients with type 2 diabetes or stress hyperglycemia." (PMID 29300728, 2018). "Type 2 diabetes (T2D) is a chronic and progressive metabolic disorder characterized by hyperglycemia and insulin insensitivity." (PMID 30153273, 2018). "Previously in type 2 diabetic patients, the wild type homozygotes had better response to rosiglitazone in terms of improvement in insulin sensitivity." (PMID 30065651, 2018). "Glucagon-like petide-1 (GLP-1) receptor agonists and DPP4-inhibitors are increasingly used therapeutic agents for type 2 diabetes, as they stimulate insulin secretion from the pancreatic beta-cells by potentiating glucose-dependent insulin secretion." (PMID 29293525, 2018). "Low-dose STZ has been known to induce a mild impairment of insulin secretion which is similar to the feature of the later stage of type 2 diabetes." (PMID 29523142, 2018). "Finally, findings suggest that AMPK may suppress inflammatory signaling in skeletal muscle, which may contribute to its insulin-sensitizing action because it is well established that obesity-linked type 2 diabetes is associated with a low-grade chronic inflammatory state." (PMID 29242278, 2018). "In elderly with type 2 diabetes, high prevalence rate of IAA was frequently accompanied with insulin treatment, while ICA and GADA were more closely associated with the systemic inflammation and beta-cell failure, respectively." (PMID 29887833, 2018). "Asian patients with type 2 diabetes are generally characterized by defective early phase insulin secretion, DPP-4 inhibitors can improve impaired insulin secretion and then exert greater effects in HbA1c in patients with type 2 diabetes." (PMID 29780322, 2018). "Therapeutic efforts to decrease adipose tissue inflammation, lipolysis or MEK/ERK signaling would likely contribute to improved insulin resistance and decreased severity of type 2 diabetes." (PMID 29661693, 2018). "Linkage disequilibrium score regression analysis revealed genetic correlations with obesity, fasting insulin, type 2 diabetes, lipid levels and coronary artery disease, indicating shared genetic architecture between metabolic traits and PCOS." (PMID 30566500, 2018). "A thematic synthesis of studies was conducted exploring the views and experiences of people with type 2 diabetes and of healthcare professionals on insulin use and management in the context of primary care." (PMID 29788908, 2018). "We assessed the cost-effectiveness of the glucagon-like peptide 1 receptor agonists liraglutide 1.8 mg and lixisenatide 20 μg (both added to basal insulin) in patients with type 2 diabetes (T2D) in Sweden." (PMID 29408938, 2018). "Urata H, Mori K, Emoto M, Yamazaki Y, Motoyama K, Morioka T, Fukumoto S, Koyama H, Shoji T, Ishimura E, Inaba M. Advantage of insulin glulisine over regular insulin in patients with type 2 diabetes and severe renal insufficiency." (PMID 29527102, 2018). "Our results indicate and confirm RCT data that lixisenatide add on basal insulin treatment can improve glycemic control in a population with long-standing type 2 diabetes and previously uncontrolled on other insulin therapeutic modalities." (PMID 29563974, 2018). "Evidence-based recommendations for insulin intensification strategies after basal insulin in type 2 diabetes." (PMID 29527102, 2018). "Despite insulin’s long-term availability and still disappointing outcomes, we believe that achieving glycemic goals in insulin users with type 2 diabetes is within reach." (PMID 29682315, 2018). "It was indeed clearly demonstrated in type 2 diabetes that signal transduction of the metabolic pathway of insulin is reduced when insulin receptors and IRS-1 or IRS-2 are serine-phosphorylated instead of tyrosine-phosphorylated." (PMID 29971102, 2018).
type 2 diabetes (continued). "Overall, both type 1 and type 2 diabetes require daily treatment to match insulin availability to carbohydrate intake." (PMID 32232090, 2018). "Type 2 diabetes is characterized by hyperglycemia accompanied by systemic resistance to insulin and β-cell dysfunction including abnormality of insulin secretion and sensitivity to glucose." (PMID 29536426, 2018). "By contrast, the blood glucose concentrations of diabetic patients are chronically elevated to approximately 12–19 mM, primarily as a result of either inadequate insulin production (type 1 diabetes) or insensitivity to the actions of insulin (type 2 diabetes)." (PMID 29924852, 2018). "The pathogenesis of type 2 diabetes is a continuous process, during which blood glucose levels gradually rise due to increasing insulin resistance and decreasing beta cell function." (PMID 29379988, 2018). "Several rodent models mimicking type 2 diabetes and metabolic syndrome display both hyperinsulinemia and insulin resistance in various organs concomitant with cardiac insulin resistance and myocardial contractile dysfunction." (PMID 29484207, 2018). "Another study supports our findings showing meaningful improvements in eating behavior after a three-month mindful eating intervention in non-insulin requiring patients with type 2 diabetes in a small cohort (n < 30)." (PMID 30081574, 2018). "The available non-insulin injectable medications for type 2 diabetes include pramlintide and several medications in the class of glucagon-like peptide-1 receptor agonists (GLP-1 RAs)." (PMID 30294713, 2018). "Information on the associations between fasting insulin and HOMA-IR with incident type 2 diabetes is scarce." (PMID 29018885, 2018). "About 85-95% of the global prevalence of diabetes is attributed to Type-2 Diabetes (T2D), which results from the body’s failure to adequately respond to insulin." (PMID 29513874, 2018). "In our data sets, there were missing data for one fasting insulin SNP (rs1530559), four type-2 diabetes SNPs (rs2972156, rs34706136, rs11257658, rs144613775) and one total cholesterol SNP (rs7570971)." (PMID 29531326, 2018). "Propanoic acid is associated with a significant immunoregulatory activity and enhanced tissue sensitivity to insulin which makes it beneficial in the context of obesity and diabetes type 2." (PMID 30531924, 2018). "The key finding of this study was non-linearity of the associations of FPG and HbA1c with incident type 2 diabetes, in contrast to 2hPG, loge fasting insulin and loge HOMA-IR, which were all linearly associated with incident type 2 diabetes." (PMID 29018885, 2018). "Some studies reported increased levels of glucose, HbA1c and low insulin activity, in type 2 diabetes, after the consumption of large amounts of fish oil (around 10 g/day)." (PMID 29713249, 2018). "Item 6 would understandably be denied by many type 2 diabetes patients whose treatment is mainly based on oral medication; this item focuses on not only oral medication but also on insulin injection and their continuation." (PMID 30123316, 2018). "The receptor is a well-established target for treatments of type 2 diabetes (T2DM) for its roles in modulating insulin sensitivity in peripheral tissues." (PMID 30906767, 2018). "In both populations, individuals with LADA were younger at diagnosis, had lower C-peptide concentrations and were more often on insulin treatment than individuals with type 2 diabetes." (PMID 29589073, 2018). "Further studies which involve the assessment of the effect of the extracts on glucose uptake and GLUT 4 translocation in an insulin resistant model is important to establish the therapeutic benefit in type 2 diabetes." (PMID 30126082, 2018). "Transgenic mice with skeletal muscle overexpression of OGT demonstrated increased levels of serum insulin, indicating hyperinsulinemia, which is characteristic in type II diabetes." (PMID 30237786, 2018).